TIGIT (T cell immunoreceptor with Ig and ITIM domains)
Diseases named in the same sentence as TIGIT in open-access papers (continued):
Sharing a sentence is not in itself a finding about the gene and the disease.
tumor (continued). "It is proposed that TIGIT may take part in tumor progression in some solid tumors and hematologic malignancies, including refractory multiple myeloma, metastatic NSCLC, esophageal cancer, cervical cancer, and melanoma." (PMID 40243372, 2025). "Furthermore, studies involving MC38 and other tumor models have revealed that therapeutic strategies targeting TIGIT—including monoclonal antibody blockade, gene knockout, and combination therapies—possess significant therapeutic potential." (PMID 40463500, 2025). "Ongoing trials are evaluating whether adding a second checkpoint inhibitor (such as an anti-CTLA-4 antibody) to PD-1 blockade plus chemotherapy can deepen responses, or if novel checkpoints (LAG-3, TIGIT, etc.)might further augment anti-tumor immunity in BTC." (PMID 41007662, 2025). "Thus, inhibiting the TIGIT pathway has emerged as a compelling approach for revitalizing anti-tumor immunity." (PMID 40567374, 2025). "Moreover, as compared to anti-PD-1-treated tumors, the combination of anti-PD-1 plus anti-ACBP/DBI reduced the expression of TIGIT on tumor-infiltrating Th cells." (PMID 40628264, 2025). "Furthermore, TILS isolated from patients with PM express significantly higher levels of TIGIT compared to tumour-free lung tissue." (PMID 39939955, 2025). "Moreover, within the TME, TIGIT mediates tumor immune escape through dual mechanisms: direct inhibition of effector CD8+ T cells and augmentation of the immunosuppressive properties of Tregs." (PMID 41425253, 2025). "Similarly, dual immune checkpoint blockade, such as targeting PD-1 in combination with CTLA-4, LAG-3, TIM-3, or TIGIT, has shown potential in restoring anti-tumor immunity, particularly in refractory settings." (PMID 40723175, 2025). "Intriguingly, a mouse tumor model experiment indicated that anti-TIGIT antibody exerts significant anti-tumor effects combined with 3 × 8Gy radiation plus anti-PD-L1 treatment only, and no benefit was observed in anti-TIGIT antibody plus 2 × 12Gy radiation plus anti-PD-L1 treatment." (PMID 40927713, 2025). "In addition to its role as a prognostic marker, the overexpression of the PVR gene and its serum levels in MM points to its implication in immune evasion and tumor aggressiveness by interacting with immune checkpoint receptors such as TIGIT and CD96." (PMID 40369504, 2025). "Notably, TIGIT+ NK cells showed markedly reduced tumor-killing efficiency compared to TIGIT- NK cells." (PMID 40231264, 2025). "Previous studies have demonstrated a coordinated expression of PD-L1 and TIGIT in tumor tissues." (PMID 39847233, 2025). "Tumor cells upregulate PD-L1 expression via genomic amplification, PTEN loss leading to PI3K pathway activation, or interferon signaling induction; other checkpoints like LAG-3, TIM-3, TIGIT are often co-expressed on exhausted T cells, synergistically inhibiting anti-tumor immunity." (PMID 41567982, 2025). "We hypothesize that the high expression of TIGIT or PD-1 on peripheral CD8 T cells at baseline in responders could be an indication that they are tumor specific and therefore indicative of response to PD-1 blockade." (PMID 40944710, 2025). "In summary macrophages from BM of all 3 solid tumors and of the MM lesions were also found to express two target molecules of the TIGIT pathway more frequently in each tumor type than in NMC aspirates (BC: TIGIT, PVRL4; PC: TIGIT, PVRL4; NSCLC: CD112, CD155; MM: TIGIT, CD155)." (PMID 40274631, 2025). "Additionally, TIGIT expression on Tregs enhances cancer metastasis and suppresses anti-tumor immunity by inducing IL-32 expression." (PMID 40317077, 2025). "Blockade of CD39 and TIGIT could represent an interesting approach to increase anti-tumor immunity in BM." (PMID 40274631, 2025). "Additionally, TIGIT expression correlates with tumor stage, survival, and TIL composition in several malignancies." (PMID 41357215, 2025).
tumor (continued). "Future studies should explore whether IL-1R8 knockout synergizes with other edits, such as PD-L1 suppression or TIGIT deletion, to form a robust resistance program against tumor-induced suppression." (PMID 40723807, 2025). "Research has revealed that F. nucleatum, present in the TME, promotes tumor cells immune escape, they can use Fap2 protein to directly interact with T cell immunoglobulin and ITIM domain (TIGIT) expressed on NK cells and T cells to inhibit the tumor-killing activity." (PMID 39921821, 2025). "In addition, VV-scFv-TIGIT in combination with PD-1 inhibition or LAG-3 inhibitors was investigated for anti-tumor efficacy in colon tumor models." (PMID 40821119, 2025). "This association supports the hypothesis that TIGIT+ CD8+ T cells represent a prominent immune phenotype in CRC and reinforces their potential role in mediating T cell exhaustion within the tumor microenvironment." (PMID 40799645, 2025). "Furthermore, anti-TIGIT treatment prompted an augmentation in effector CD8+ T cells within the tumor tissue (P < 0.05)." (PMID 39939322, 2025). "Preclinical studies have demonstrated that blocking both TIGIT and PD-1 significantly enhances tumor-specific T cell proliferation, degranulation, and cytokine production.The adverse reactions to Tiragolumab are similar to those of other ICIs, including fatigue, chills, and nausea." (PMID 40677703, 2025). "Furthermore, immune checkpoint analysis revealed that ALDOA-high tumors exhibit reduced expression of key immune checkpoints, including PDCD1, CTLA4, and TIGIT, potentially reducing immune cell engagement with the tumor and further promoting immune evasion." (PMID 41239433, 2025). "In addition, in another study, anti-TIGIT antibody treatment significantly reduced tumor volume by restoring CD8+ T-cell function, thereby improving survival in treated mice." (PMID 39531203, 2025). "Anti-TIGIT antibody reshapes the tumor microenvironment by enhancing the blocking effect of PD-L1 on bone marrow cells and Treg cells, thereby improving the prognosis of tumor patients." (PMID 40129984, 2025). "Besides its ability to inhibit tumor killing by effector T and NK cells, TIGIT is involved in regulating the function of Tregs." (PMID 40890162, 2025). "High expression of PD-1 and TIGIT on CD8+ T cells from responders could indicate that the cells were tumor specific and that T cells were activated." (PMID 40944710, 2025). "There was concurrent and significantly increased expression of the immune checkpoint pathway markers HAVCR2 (TIM-3), CTLA-4, PDCD1 (PD-1), PDCD1LG2 (PD-L1), LAG3, and TIGIT, demonstrating increased immune suppressive signaling from both the tumor and immune cell populations." (PMID 38418892, 2025). "This pro-tumor stromal configuration, aside from its close association with cancer cells, promotes an immunosuppressive TME by releasing inhibitory signals, particularly PVR, which engages with TIGIT on immune cells and suppresses their functions." (PMID 40107247, 2025). "To further dissect the immunoregulatory role of TIGIT in the tumor microenvironment, we analyzed scRNA-seq data from CRC patients (GSE178341), analysis revealed that TIGIT expression was predominantly localized to TNKILCC cells, a T cell population enriched in exhausted and cytotoxic features." (PMID 40799645, 2025). "Its anti‐tumour negative regulation makes TIGIT a potential cancer treatment target." (PMID 40415479, 2025). "TIGIT could lead to NK cell depletion during tumor progression, and further studies revealed that an anti-TIGIT monoclonal antibody could reverse NK cell depletion and be used in immunotherapy for a variety of tumors." (PMID 39910672, 2025).
tumor (continued). "Similarly, TIGIT also showed elevated expression in the tumor-infiltrating CD8+ T cell population (PBMCs: 50.1%; TILs: 65.6%)." (PMID 41300994, 2025). "For that reason, TIGIT is known as a key inhibitor of anti-tumor responses." (PMID 40079005, 2025). "TIGIT blockade in combination with radiotherapy has been investigated in both cancer tumor models and in mouse models through activation of the cGAS-STING pathway, induction of chemokine expression, and release of nuclear high-mobility protein from the box-1 group." (PMID 40870970, 2025). "Moreover, TIM‐3 and TIGIT mediate some downregulatory processes in tumor microenvironment, which result in the inhibition of T cells." (PMID 40243372, 2025). "They found that co-inhibitory receptors PD-1, TIM-3, LAG-3, and TIGIT were expressed at relatively low levels on B cells in both tumor and non-tumor tissues, with some indication of increased expression on B cells isolated from tumor tissue." (PMID 41008839, 2025). "However, the combined treatment strategy of PD-1 inhibitors and TIGIT inhibitors can increase the number of tumor-infiltrating CTLs, significantly inhibit tumor growth, and prolong the survival of mice." (PMID 41514551, 2025). "In addition to the blocking effect of the two monospecific antibodies, bsAbs can connect immune cells to tumor cells and enhance cross-talk between TIGIT+ T cells and PD-L1+FcRs+ DCs, which further promoted anti-tumor activity." (PMID 40890162, 2025). "However, further investigations are necessary to better dissect the pathways of DNAM-1/TIGIT balance that affects NK cell anti-tumor function." (PMID 40421025, 2025). "Similarly, binding of TIGIT on T cells to CD155 on tumor cells and APCs can downregulate activation of ZAP70 and NF-κB in T cell intracellular signaling, which in turn inhibits T cell activation." (PMID 40276607, 2025). "Additionally, early-stage experimental models indicate that combining TIGIT blockade with PD-1 or PD-L1 inhibitors produces a synergistic effect, resulting in improved anti-tumor responses." (PMID 41550427, 2025). "Some studies have shown that co-expression of TIGIT and PD-1 could lead to impaired protective anti-tumor responses; therefore, antibody co-blockade of TIGIT and PD-1 could enhance CD8+ T-cell effector function, resulting in significant tumor clearance." (PMID 40236710, 2025). "Notably, however, the frequency of TNF-α, and IFN-γ producing T cells was increased for ABE-TILs upon co-culture with autologous tumor lines naturally expressing TIGIT or TIM3-specific ligands (i.e., CD112 and CD155 and galectin-9, respectively)." (PMID 41394272, 2025). "Even if the effects by a TIGIT blockade are promising further synergistic immunologic pathways need to be identified to establish multi-specific targeting strategies to enhance and stabilize anti-tumor immunity." (PMID 40274631, 2025). "However, tumor-infiltrating NK cells from metastatic lymph node patients exhibit elevated TIGIT expression, indicating a role in immune suppression." (PMID 40677703, 2025). "Similarly, T cell immunoglobulin and ITIM domains (TIGIT) on T cells can engage CD155 expressed on tumor cells and APCs to recruit SH2-containing inositol phosphatase-1 (SHIP1) to inhibit T cell signaling and activation." (PMID 40276607, 2025). "TIGIT may be co-expressed in tumor cells alongside other receptors, including PD-1, TIM-3, and LAG-3." (PMID 40574024, 2025). "Initial clinical trial results suggest that TIGIT inhibition may enhance T cell and NK cell function, restore anti-tumor immunity, and offer synergistic benefits with existing immunotherapies." (PMID 40567374, 2025). "Preclinical evidence also shows that TIGIT is often co-expressed with PD-1 on tumour-specific CD8+ T cells, and combined TIGIT/PD-1 blockade may enhance anti-tumour activity." (PMID 40647497, 2025).
tumor (continued). "This inhibitory phenotype refers to a functional state in which NK cells exhibit reduced cytotoxicity and cytokine production due to the upregulation of inhibitory receptors—such as NKG2A, TIGIT, or PD-1—and the influence of immunosuppressive signals within the tumor microenvironment." (PMID 40299429, 2025). "MK-7684A is a fixed dose compound formulation composed of Merck Vibostolimab (MK-7684) and Pembrolizumab (K-drug), which can block the interaction between TIGIT/PD-1 and its ligand, thereby activating T lymphocytes and enhancing the attacking ability of tumor cells." (PMID 40356928, 2025). "In tumour Treg cells, both anti-TIGIT isotypes drove downregulation of immunosuppressive and Treg-cell-associated genes such as Il10, Ctla4 and Tnfrsf1b relative to treatment with anti-PD-L1 antibodies or control, and sustained those effects in combination with anti-PD-L1." (PMID 38418879, 2024). "In addition, TIGIT interferes with tumor recognition by NK cells through competitive inhibition of CD226." (PMID 39906665, 2024). "Interestingly, CAR-NKs showed near-100% expression of TIGIT, which in NK cells has been directly shown to reduce cytotoxicity during chronic tumor stimulation unless countered with an anti-TIGIT antibody blockade." (PMID 38627969, 2024). "Thus, IL-15 induction combined with TIGIT inhibition promotes NK cell degranulation and impedes tumour metastasis." (PMID 38893071, 2024). "Dual blockade of the PD-1 and TIGIT enhance the anti-tumor ability of CD8+ T cells." (PMID 39391310, 2024). "In addition, TIGIT has also been described on exhausted T cells in tumor diseases, especially in the context of its involvement in various immunosuppressive mechanisms like promoting dysfunctional phenotypes in macrophages or NK cells." (PMID 39518969, 2024). "Our data suggested macrophages and other myeloid cells might mediate the effects of anti-TIGIT antibodies on the anti-tumour T cell response." (PMID 38418879, 2024). "Moreover, several ICPs such as Lag-3 and TIGIT were up-regulated in NK cells from tumor-bearing mice." (PMID 39196934, 2024). "However, chronic TIGIT engagement with its ligands in a tumour microenvironment leads to a functional decline in NK cells." (PMID 38540243, 2024). "Furthermore, F. nucleatum inhibits helper T cells and cytotoxic T lymphocytes through Fap2-mediated TIGIT interactions, inducing lymphocyte apoptosis and increasing tumor growth." (PMID 39872848, 2024). "ICB drugs such as anti‐CTLA4/LAG3/TIGIT antibodies may be effective considering their high expression on tumor reactive T cells." (PMID 39136172, 2024). "Tumor-infiltrating CD8+ T cells in HBV-associated HCC were highly activated but dysfunctional, showing impaired cytotoxicity and exhaustion, with significantly increased expression of immune checkpoint molecules, such as PD-1, CTLA-4, LAG-3, and TIGIT." (PMID 38793588, 2024). "The results showed that both the volumes and weights of formed CRC tumor nodes were reduced by anti-TIGIT or sulfarotene, which could be further augmented by the combination of treatment with anti-TIGIT and sulfarotene." (PMID 38543173, 2024). "TIGIT is also highly expressed on the surface of tumor-infiltrating T cells." (PMID 38724599, 2024). "Tumour-infiltrating T lymphocytes and NK cells express TIGIT in lung tissues." (PMID 38540243, 2024). "Additionally, we included the PD-1 blocking mAb EH12.2H7 (BioLegend) into our testing as several ex vivo studies recently suggested that blockade of TIGIT in the tumor microenvironment synergizes with the blockade of other CR inhibitors." (PMID 38967649, 2024). "HB-0036 allows a greater accumulation of anti-TIGIT Ab at the tumor site through the co-engagement of PD-L1 on tumor cells with the anti-PD-L1 arm of bsAb, leading to high local drug concentrations, when compared to combination therapy with the two parental antibodies." (PMID 38257366, 2024).
tumor (continued). "The mechanisms could be that TIGIT blockade reversed the suppressed glucose metabolic activity of T cells, induced apoptosis, and reduced G2/M transit in tumor cells." (PMID 38229100, 2024). "Building upon this, the incorporation of a triple therapy regimen comprising radiotherapy, anti-PD-1, and anti-TIGIT has presented promising results in various tumor-bearing models, despite the fact that optimizing the radiotherapy strategy required careful consideration to ensure its effectiveness." (PMID 38229100, 2024). "TIGIT-nectin axis hampers T and NK effector function, thereby exacerbating tumor immune escape." (PMID 38167055, 2024). "Moreover, changes in vascularization, cytokine expression, and the upregulation of inhibitory factors such as PD‐1, PD‐L1, and TIGIT contribute to impairing NK cell function within the tumor." (PMID 39588940, 2024). "TIGIT is an inhibitory regulator highly expressed in human and murine tumor infiltrating T cells." (PMID 38169590, 2024). "Likewise, the density of TIGIT+ T cells was similar between primary (n = 36) and metastatic (n = 36) tumor tissue in unmatched as well as matched-pair (n = 15) analysis." (PMID 39105820, 2024). "Additionally, CTL tumor cells also displayed TIGIT expression after recurrence, resulting in a heightened interaction between TIGIT on tumor cells and CD155/PVR on monocytes." (PMID 38464517, 2024). "In addition, the results of IHC analysis showed that the expressions of CD8, GLUT1, HK2, PKM2 and LDHA were significantly up-regulated in tumor tissues treated with anti-TIGIT mAb." (PMID 38216949, 2024). "Therefore, we believe that ZGGS15 is expected to block LAG-3 and TIGIT in immune cells binding to their ligands to exert anti-tumor activity." (PMID 38724599, 2024). "Using TCGA PanCancer transcriptomic data, we found that TIGIT mRNA levels are relatively high in ccRCC compared to most other tumor types, and that TIGIT expression was positively correlated with higher histologic grade and stage, in accord with prior single-cell transcriptomic findings." (PMID 39105820, 2024). "Blocking TIGIT can reverse NK cell depletion and stimulate anti-tumor immunity." (PMID 39221244, 2024). "In congruence with this notion, numerous preclinical models have shown that administering anti-TIGIT antibodies alongside anti-PD-1 or PD-L1 inhibitors results in nearly complete tumor remission, whereas treatment with anti-TIGIT antibodies alone elicits limited efficacy." (PMID 38627681, 2024). "Notably, IL‐15 stimulation combined with TIGIT blockade reinvigorates CD8+ TIL‐mediated antitumour immunity in tumour‐bearing mice and LUAD organoids." (PMID 38279870, 2024). "Moreover, in vivo administration of the blocking antibody against TIGIT not only inhibits tumor growth but also augments the functionality of CD8 + T lymphocytes." (PMID 38216949, 2024). "Additionally, we observed that the spatial distribution of TILs co-expressing PD1 with LAG3 and/or TIM3 and/or TIGIT influences outcomes, with closer proximity to tumor cells indicating worse clinical benefit." (PMID 39591972, 2024). "In this study, we presented a novel trispecific NK cell-engaging antibody B7-H3xTIGITxCD16, which can simultaneously activate NK cells through CD16 binding, block the inhibiting NK checkpoint molecule TIGIT, and redirect NK cells towards B7-H3-positive tumor cells." (PMID 38474651, 2024). "Dmitrij and colleagues found that TIGIT was upregulated in tumor-infiltrating CD8+ T cells." (PMID 39845973, 2024). "Furthermore, TIGIT expression was found to be upregulated in CD8+ T-cells at tumour sites in patients with GBM compared with healthy controls." (PMID 38660136, 2024). "manifest that Fusobacterium nucleatum (FN) binds to the inhibitory receptor TIGIT on human natural killer cells and T cells through Fap2 protein, which inhibits the cytotoxicity of natural killer cells, thus inhibiting the anti-tumor immune function of the body and leading to tumor occurrence." (PMID 39175566, 2024).